TRIM69 (tripartite motif containing 69)
Diseases named in the same sentence as TRIM69 in open-access papers (continued):
Sharing a sentence is not in itself a finding about the gene and the disease.
infection (5 papers, 2019 to 2025). The state of being infected such as from the introduction of a foreign agent such as serum, vaccine, antigenic substance or organism. "In addition, TRIM69-depleted mice were significantly more susceptible to infection by DENV." (PMID 38932287, 2024). "Rather, the modest increase in infection observed when this response was inhibited by αTAT1 KO suggests that this response may be antiviral in nature, despite it being unnecessary for TRIM69 restriction." (PMID 39804091, 2025). "However, in contrast to bortezomib, ruxolitinib did modestly increase the amount of VSIV infection in the presence of TRIM69 (increasing the titer ∼2.5-fold)." (PMID 31375575, 2019). "This parental virus stock was potently inhibited by TRIM69 following overnight infection." (PMID 31375575, 2019). "In this way, IFN-induced TRIM69 might inhibit natural VSIV infections and similarly influence the safety and/or efficacy of therapeutic interventions (based upon VSIV)." (PMID 31375575, 2019). "Thus, the majority of the apparent ∼7-fold rescue was caused by reduced infection in the absence of TRIM69 (as opposed to ruxolitinib solely enhancing infection in the presence of TRIM69)." (PMID 31375575, 2019). "To determine which step TRIM69 restricts HIV-1, we infected THP1 and isolated DNA 24 h post-infection." (PMID 39804091, 2025). "Consistent with that conclusion, infection of HT1080 cells with VSVIND and Western blot analysis 6 h later revealed that VSVIND matrix (M) protein expression was profoundly inhibited by TRIM69." (PMID 31578292, 2019). "Visual inspection of the titration curves indicated that the majority of the rescue was due to reduced VSIV infection in control cells (in the presence of bortezomib), as opposed to proteasomal inhibition actually enhancing infection in the presence of TRIM69." (PMID 31375575, 2019). "When normalized to infection in the absence of TRIM69, proteasomal inhibition appeared to partially rescue the restriction of VSIV." (PMID 31375575, 2019). "As with bortezomib, some toxicity was observed, and ruxolitinib slightly reduced the level of infection in the absence of TRIM69." (PMID 31375575, 2019). "As our data demonstrate that microtubule acetylation is not directly exploited by HIV-1 during infection nor required for TRIM69-mediated restriction of HIV-1, the mechanism by which microtubule acetylation is induced during infection remains unclear." (PMID 39804091, 2025). "Importantly, this lack of TRIM69 sensitivity was observed while parallel cultures (of the equivalent cells) fiercely resisted VSIV infection." (PMID 31375575, 2019). "Notably, while VSIV-GFP infection was reduced by >100-fold by TRIM69, the other viruses in our panel [influenza A virus A/Puerto Rico/8/1934 (H1N1) (PR8), Rift Valley fever phlebovirus (RVFV 35/74), and HIV-1 (NHG)] were unaffected by TRIM69 expression." (PMID 31375575, 2019).
tumor (4 papers, 2023 to 2025). "LncFAL inhibits ex vivo anti-tumor activity by directly binding to and competitively attenuating FSP1-dependent Trim69 ubiquitination, reducing susceptibility to ferroptosis and inhibiting ex vivo anti-tumor activity." (PMID 40191204, 2025). "The results of the present study indicate that TRIM69 is differentially expressed in different tissue types and in tumor tissues according to pathologic stage or M stages, albeit not statistically associated with OS or DFS." (PMID 37653392, 2023). "We also provide evidence that high expression of TRIM69 in PDAC is an independent predictor of tumor aggressiveness with significant hazard ratios for predicting clinical outcome." (PMID 36741265, 2023). "We characterize the inhibitory role of TRIM69 in the EYA4-driven tumor suppression through genetic and biochemical approaches as well as in vitro and in vivo studies." (PMID 36741265, 2023). "The results of immunohistochemical staining analysis and immunohistochemical scoring supported the findings from RT-qPCR for TRIM69 different expression between tumor tissues and normal tissues." (PMID 37653392, 2023). "Consistent with this, the mRNA expression level of TRIM69 was low in tumor tissue." (PMID 37653392, 2023). "Since TRIM69 elicits polyubiquitylation and turnover of EYA4, it is plausible that tumor-suppressive roles of EYA4 could be blocked by TRIM69." (PMID 36741265, 2023). "Our experiments also provide evidence that TRIM69 may improve the tumor immune microenvironment through the immune response, specifically the NOD-like receptor signaling pathway." (PMID 37653392, 2023). "Still, whether TRIM69 can inhibit tumor development through immune-related effects remains to be confirmed by further studies." (PMID 37653392, 2023). "Thus, TRIM69 impedes tumor-suppressive phenotypes of EYA4 in vivo." (PMID 36741265, 2023). "TRIM69, Ube2j1, ZBTB4, and SKP2 show the most pronounced effects on the immune microenvironment of the tumor." (PMID 40697329, 2025). "Moreover, the differential expression of TRIM69, Ube2j1, ZBTB4, and SKP2 likely serves a critical function in modulating tumor immune infiltration." (PMID 40697329, 2025). "A similar upregulation of TRIM69 was also observed in two PDAC cohorts from NCBI's Gene Expression Omnibus (GEO) database, in which GSE15471 contained 40 tumor tissues and 39 normal pancreatic tissues, and GSE16515 included 36 tumor tissues and 17 normal pancreatic tissues." (PMID 36741265, 2023). "Although TRIM69 has been identified in various processes and pathways related to tumorigenesis, to our knowledge, the involvement of TRIM69 in tumor development remains incompletely understood and has not been studied in CRC." (PMID 37653392, 2023). "Although exact evidence for the relationship between TRIM69 and the NOD-like receptor-signaling pathway is lacking, we can speculate that TRIM69 may be involved in the anti-tumor response via the NOD-like receptor-signaling pathway." (PMID 37653392, 2023). "Subsequently, tumor and paraneoplastic tissues from COAD patients collected during clinical consultation were subjected to real-time quantitative reverse transcription PCR (RT-qPCR) analysis and immunohistochemistry to detect TRIM69 expression at different levels." (PMID 37653392, 2023). "Our current study validate TRIM69 as a mutually exclusive E3 ligase targeting EYA4 for polyubiquitylation and turnover, thereby perturbing its ability to deactivate β-catenin/ID2 pathway and suppress cell proliferation, self-renewal as well as tumor development of PDAC cells." (PMID 36741265, 2023).
TRIM69 also shares sentences with these, for which no sentence is quoted: cardiac diseases (1 paper); COVID-19 (1); gastric cancer (1); lung adenocarcinoma (1); sarcoma (1).